LGALS3 (galectin 3)
Diseases named in the same sentence as LGALS3 in open-access papers (continued):
Sharing a sentence is not in itself a finding about the gene and the disease.
atherosclerosis (continued). "Among these proteins, a few studies investigated mainly the roles played by galectin-1 (Gal-1) and galectin-3 (Gal-3) in the molecular mechanisms of atherosclerosis and in brain tissue remodeling after a stroke event." (PMID 35281427, 2022). "It is well-known that galectin-3 plays an important role in atherosclerosis development (the dark and bright of calcification)." (PMID 35685493, 2022). "Galectin-3 is involved in lipid accumulation and chronic inflammation, which can be worsened in regular hemodialysis patients leading to arterial stiffness and atherosclerosis." (PMID 35455752, 2022). "Endothelial cells, macrophages, and vascular smooth muscle cells (VSMCs) are three most important cells in the process of atherosclerosis pathology, and galectin-3 affects all these kinds of cells." (PMID 35685493, 2022). "As smooth muscle cells and galectin-3 play an important role in a variety of plausible mechanisms of atherosclerosis and chronic heart diseases." (PMID 35771146, 2022). "Activated galectin-3 gene expression was observed in the smooth muscle cells of the hypercholesterolemic and artificially injured aorta, which indicates the involvement of galectin-3 in the process of developing atherosclerosis." (PMID 35208606, 2022). "Galectin-3 (Gal-3), a β-galactoside-binding lectin whose levels increase with ageing, plays a significant role in systemic inflammation, fibrosis, atherosclerosis, and HF progression." (PMID 36261756, 2022). "Galectin-3 seems to be an important and, at the same time, useful biomarker of atherosclerosis and its special role has been observed in the process of atheromatous plaque destabilisation." (PMID 35053194, 2021). "Next, the NE-SPIO-PEG formulation was functionalized with a fully human scFv-Fc antibody (P3) recognizing galectin 3, an atherosclerosis biomarker." (PMID 34068875, 2021). "Over the years, the participation of many inflammatory condition markers in the atherosclerotic process has been studied and then a potential role of galectin-3 as a mediator of atherosclerosis has been suggested." (PMID 35053194, 2021). "Endothelial dysfunction is reportedly caused by several mechanisms, including inflammation, dysregulated vascular remodeling, and vascular growth; in atherosclerosis, galectin-3 induces endothelial dysfunction." (PMID 34437403, 2021). "Rationale: The high expression of Galectin-3 (Gal3) in macrophages of atherosclerotic plaques suggests its participation in atherosclerosis pathogenesis, and raises the possibility to use it as a target to image disease severity in vivo." (PMID 33408786, 2021). "P3 specifically targets galectin-3, a protein that has been highlighted in recent studies as a new atherosclerosis biomarker." (PMID 34068875, 2021). "In this study, we found that thrombin activated MAPK signaling pathways and increased the expression of galectin-3, which was also a well-known factor in atherosclerosis." (PMID 34746246, 2021). "Abundant literature supports a profibrotic role of galectin-3 in a wide range of pathologies and suggests a plausible protective role for this modulatory protein in advanced atherosclerosis through supporting plaque stability." (PMID 32295421, 2020). "Collectively, these findings delineate galectin-3 as a negative regulator of inflammation and macrophage invasion that opposes adverse atherosclerosis progression and confirms MMP12 as a potential target for medical intervention of atherosclerosis." (PMID 32295421, 2020). "Further, our studies allow us to reinterpret the meaning of Lgals3 in SMC phenotypic transitions in the context of atherosclerosis." (PMID 32674599, 2020). "This relationship is further strengthened by prior observations that plasma Galectin-3 is independently related to various systemic arterial diseases in asymptomatic individuals (aortic stiffness, atherosclerosis)." (PMID 32392260, 2020).
atherosclerosis (continued). "Although the relationship between galectin-3 and atherosclerosis is not completely understood, galectin-3 plays a role in the formation and destabilization of the atherosclerotic plaque." (PMID 32294902, 2020). "Galectin-3’s interaction with hyaluronan influences the vascular smooth muscle cell phenotype in atherosclerosis and contributes to cardiac macrophage responses following ischemia-reperfusion injury, impacting vascular remodeling and cardiac repair processes relevant to diastolic dysfunction." (PMID 39063659, 2024). "Galectin-3 is also associated with macrophage differentiation absorbing oxidized low-density lipoprotein (ox-LDL) and transforming macrophages into foam cells, thereby accelerating atherosclerosis." (PMID 36873388, 2023). "Galectin-3 is a protein with pleiotropic effects on different cellular functions, including modulation of the innate immune system, fibrosis and on the development of cardiovascular disease including atherosclerosis." (PMID 37175392, 2023). "Additionally, galectin-3 contributes to the processes of atherosclerosis and arterial stiffening by impairing normal endothelial function, causing foam cell formation, and leading to VSMC proliferation and migration." (PMID 37240626, 2023). "In this study, we demonstrated that very early values of galectin-3 in the blood (on day 1 and 5) correlate mostly with atherosclerosis factors (such as HTA and triglyceride levels), while on day 30 this biomarker correlates with diastolic dysfunction and “announces” left ventricular remodeling." (PMID 35208606, 2022). "Galectin-3 was reported to directly affect the functioning of the three cell types involved in the development of atherosclerosis, i.e., the dysfunction of endothelial cells, differentiation of monocytes to macrophages and foam cells, and proliferation and migration of vascular smooth muscle cells." (PMID 36272642, 2022). "Advances in the in vivo targeting efficiency of agents against proteins overexpressed in the plaque, such as galectin-3, could also improve the assessment and monitoring of atherosclerosis." (PMID 34068875, 2021). "Secondly, this study didn't assess the expression of the LGALS-3 gene in tissues, therefore, it was not possible to withdraw from this study that significant rs4652 in the LGALS-3 gene affected its heart tissue expression and were directly involved in fibrosis, inflammation, and atherosclerosis." (PMID 34616230, 2021). "In conclusion, we highlight a profibrotic role for galectin-3 in atherosclerosis." (PMID 32295421, 2020). "In apolipoprotein E-deficient mice (a model of experimental atherosclerosis) galectin-3 is expressed in macrophage-rich areas, but not in smooth muscle cell-rich areas of aortic roots and brachiocephalic arteries." (PMID 28471381, 2017). "The role of galectin-3 in atherosclerosis deserves special attention." (PMID 28471381, 2017). "Several studies have suggested that the measurement of plasma galectin-3 concentrations may be a good biomarker of diseases related to atherosclerosis." (PMID 28471381, 2017). "In summary, the data suggest that galectin-3 may act not only as an inflammatory marker but also as an active participant in the pathophysiology of atherosclerosis, indirectly influencing lipid metabolism—particularly in the context of low HDL-C and elevated non-HDL cholesterol." (PMID 40699731, 2025). "Rare cells expressing FB-like (I-cluster 12, Pi16+, Igfbp4+, and Dpep1+) or MΦ-like genes (I-cluster 14, Lgals3+, Cd68+, and Ptprc+) had low expression of the eYFP lineage label, suggesting that these cells were not derived from VSMCs, similar to what has been proposed in atherosclerosis." (PMID 40577585, 2025).
atherosclerosis (continued). "In vascular calcification, galectin-3 promotes calcification of vascular smooth muscle cells through the AMP-activated protein kinase/thioredoxin-interacting protein pathway, exacerbating arterial stiffness and atherosclerosis progression, crucial features linked to diastolic dysfunction." (PMID 39063659, 2024). "Thus, our work could help to clarify the role of TXNIP in the pathological process of atherosclerosis and open up a new insight into the regulatory mechanism of VSMCs calcification in combating plaque rupture by galectin-3." (PMID 35771146, 2022). "Also, Galectin-3 inhibitors may be a pos-sible therapy for atherosclerosis and cardiovascular obstacles of T2DM in the future." (PMID 34616230, 2021). "Our findings indicate that galectin-3–negative macrophages accumulate within rabbit, mouse, and human advanced plaques and show loss of galectin-3 is directly associated with detrimental plaque composition in a mouse model of atherosclerosis." (PMID 32295421, 2020). "To investigate the impact of IL11 expression on aortic inflammation, we probed for galectin-3 (LGALS3) and lysosome-associated membrane protein-2 (LAMP2) expression which are known markers for macrophages but also rarely expressed in VSMCs in response to atherosclerosis or injury." (PMID 33082445, 2020). "Moreover, galectin-3 may promote atherosclerosis through the activation of vascular smooth muscle cells by oxidized LDL particles and by inducing insulin resistance." (PMID 32294902, 2020). "Our findings lend further support to MMP12 as a pertinent therapeutic target for the prevention of clinical atherosclerosis and suggest that promoting galectin-3 expression may also represent an effective strategy to counter the actions of proinflammatory macrophages during plaque progression." (PMID 32295421, 2020). "In mechanism, both low HDL-C and high galectin-3 can induce lipid modification in oxidized LDL-C and enhance the phagocytosis of macrophages in taking up the oxidized LDL-C, exacerbating atherosclerosis and plaque rupture in vascular inflammation." (PMID 38195853, 2024). "In support of this, our data showed that serum galectin-3 levels correlated well with peripheral WBC count, circulating neutrophil count, NLR, and hsCRP levels, which are well-known markers of advanced atherosclerosis." (PMID 38195853, 2024). "When atherosclerosis was produced in mice, CARMN deletion increased the volume, size, and content of proinflammatory Lgals3 (galectin 3)-expressing cells and altered plaque composition, resulting in an advanced phenotype." (PMID 36430208, 2022). "Melatonin also suppressed galectin-3 (Gal-3), reduced the activity of the NF-κB signaling pathway and promoted the nuclear translocation of TFEB, thereby enhancing autophagy and suppressing inflammation in atherosclerosis." (PMID 41300435, 2025). "Both polarizing events depend on the KLF4-galectin-3 axis, implying that VSMC-specific targeting of KLF4/galectin-3 function could be beneficial as a therapeutic strategy in the treatment of atherosclerosis." (PMID 41155497, 2025). "The role of galectin-3 in atherosclerosis is widely observed, but the conclusion is not always consistent." (PMID 35685493, 2022). "The P3 antibody was chosen because galectin-3 is strongly expressed by the TREM2-positive foamy macrophage subset, which has been recently identified by single-cell RNA sequencing as the main immune cell subset in atherosclerosis." (PMID 34068875, 2021). "Together, these findings strongly indicate that galectin-3 acts as a negative regulator of inflammation by modulating TGFβ signaling and reducing the expression of the proinflammatory molecules MMP12, CCL2, and PTGS2 in a mouse model of atherosclerosis." (PMID 32295421, 2020). "Galectin-3 handling and VCAM-1-driven pathways overlap in leukocyte trafficking and atherosclerosis, suggesting galectin-3 and VCAM-1 may share common pathogenesis in CV mortality." (PMID 30249969, 2018).
atherosclerosis (continued). "Several other studies have shown higher levels of galectin-3 in advanced carotid atherosclerosis and demonstrated that galectin-3 is an independent biomarker of advanced atherosclerosis independent of age, sex, LDL cholesterol levels, and history of acute myocardial infarction." (PMID 36272642, 2022). "Moreover, we consistently observe that galectin-3 expression within CD68-positive cells (which we deem macrophages) is adversely diminished as plaques advance but are maintained in mouse plaque regression models, replicating observations in human atherosclerosis." (PMID 32295421, 2020). "We observed differences in the expression of galectin-3 in normal arteries, and arteries of patients with PAD, with a displacement of the expression from the adventitia to the media and the intima, which may suggest involvement of galectin-3 in the site of the atherosclerosis plaque formation." (PMID 28471381, 2017). "Moreover, there is a weak negative correlation between galectin-3, Ly/N, and, respectively, Ly/WBC; although the relationship is not very strong, it is statistically significant, suggesting again the protective role of lymphocytes against inflammation and atherosclerosis." (PMID 40430046, 2025).
melanoma (116 papers, 2008 to 2026). A malignant, usually aggressive tumor composed of atypical, neoplastic melanocytes. "Subsequent investigations have demonstrated that LAMP1 interacts with galectin-3 on the lung through polyLacNAc, which is implicated in melanoma lung metastasis." (PMID 39669571, 2024). "LAG-3, along with its ligands Galectin-3 and HLA-II, was found to be particularly expressed in melanoma lesions with inflamed T-cell phenotypes such as high-risk uveal melanoma, where Gal-3/LAG-3 interplay restricts T-cell-mediated responses." (PMID 37345056, 2023). "This study revealed that galectin-3, a galactoside-binding protein that is commonly overexpressed in many cancers including melanoma, is naturally associated with MCAM on the surface of both skin and uveal melanoma cells." (PMID 36291660, 2022). "These indicate that MCAM and galectin-3 are naturally associated on the cell surface of melanoma cells." (PMID 36291660, 2022). "Despite galectin-3 increasing metastatic potential of tumor cells by increasing its motility via metalloproteinase regulation, strong galectin-3 expression in melanoma patients was associated with improved survival." (PMID 33802954, 2021). "For example, galectin-3 binds to N-linked glycans on CD146/MCAM (Melanoma Cell Adhesion Molecule) and induces CD146 dimerization and subsequent activation of AKT (Protein kinase B) signaling." (PMID 32517158, 2020). "Galectin-3 overexpression is associated with the increased invasiveness of many types of tumor cells, including neuroendocrine tumor pheochromocytoma, ovarian, melanoma, thyroid, and colorectal cancer cells." (PMID 25669973, 2015). "Among the many differences between melan-A and Tm1 cells 19, a striking difference was the loss of galectin-3 expression through hypermethylation of a CpG island composed of 33 CpG dinucleotides located at its 5′ upstream region in the melanoma cell." (PMID 24421272, 2014). "In order to study the role of galectin-3 in tumor angiogenesis associated with tumor-associated macrophages (TAM) and tumor parenchyma, the galectin-3 expression was reconstituted in Tm1 melanoma cell line that lacks this protein." (PMID 24421272, 2014). "The protumoral role of galectin-3 was also observed in murine melanomas, engrafted in both wild type and galectin-3-deficient mice." (PMID 24764473, 2013). "LAG-3 and its ligands, Galectin-3 and MHC-II, exhibit high expression levels in melanoma lesions, particularly within inflamed T-cell phenotypes such as high-risk uveal melanoma, where the interaction between Galectin-3 and LAG-3 attenuates T-cell-mediated responses." (PMID 39743998, 2024). "Moreover, the serum level of Galectin-3 has been significantly associated with the prognosis of the melanoma patients." (PMID 22216283, 2011). "However, others have reported that galectin-3 may act as a metastasis suppressor or even sensitize BRAF-mutated melanoma cells to vemurafenib (BRAF V600E inhibitor) treatment." (PMID 33918883, 2021). "Therefore, galectin-3 host deficiency could impair the successful establishment of melanoma metastatic foci by decreasing the binding of melanoma cells onto target tissue and by enhancing NK-mediated anti-tumor response." (PMID 24982845, 2014). "In the current study, we explored the role of galectin-3 (Gal-3), a lectin that avidly binds surface poly-LacNAcs, in dictating melanoma aggressive behavior." (PMID 40430022, 2025). "GPVI and CLEC-2 have been shown to interact with e.g., galectin-3 and podoplanin, respectively, both of which are upregulated in melanoma." (PMID 39695652, 2024). "The inhibition of galectin-3 is under intense investigation as a cancer treatment approach, including immunosuppression and interference with PD-1-PD-L1 interaction in melanoma and other malignancies." (PMID 38892038, 2024). "Galectin-3 can be secreted by both tumor cells and immune cells and high galectin-3 expression mediates sensitivity to vemurafenib in melanoma cells." (PMID 38730718, 2024).